ZBTB14 (zinc finger and BTB domain containing 14)
Description:
Transcriptional activator of the dopamine transporter (DAT), binding its promoter at the consensus sequence 5'-CCTGCACAGTTCACGGA-3'. Binds to 5'-d(GCC)(n)-3' trinucleotide repeats in promoter regions and acts as a repressor of the FMR1 gene. Transcriptional repressor of MYC and thymidine kinase promoters.
Synonyms: Zfp-161; ZF5; Zfp-5; ZFP161; ZNF478
Tractability: PROTAC: UniProt records ubiquitination sites on it; ubiquitination databases record sites on it; its protein half-life has been measured.
Target class: Transcription factor
Gene: Protein-coding gene on chromosome 18 (5,288,863 to 5,297,053, reverse strand). Ensembl gene ENSG00000198081.
Subcellular location: Nucleus
Subcellular location (Human Protein Atlas): Nucleoplasm; Cytosol; Nucleoli
Gene Ontology:
Molecular function: DNA-binding transcription factor activity; protein binding; sequence-specific DNA binding; sequence-specific double-stranded DNA binding; transcription cis-regulatory region binding; DNA-binding transcription repressor activity, RNA polymerase II-specific; RNA polymerase II cis-regulatory region sequence-specific DNA binding
Biological process: negative regulation of DNA-templated transcription; negative regulation of transcription by RNA polymerase II; regulation of cytokine production; regulation of immune system process
Cellular component: nucleolus; nucleoplasm; nucleus
Genetic constraint (gnomAD): Loss-of-function variants: 5 observed, 11.28 expected, observed/expected ratio (o/e) 0.44, 90% interval 0.23 to 0.93. The upper end of that interval is the gene's LOEUF score, 0.93, which puts it in group 3 of 6, group 1 being the genes least tolerant of losing a copy. Missense variants: 95 observed, 185.05 expected, observed/expected ratio (o/e) 0.51, 90% interval 0.43 to 0.61. Synonymous variants: 60 observed, 60.67 expected, observed/expected ratio (o/e) 0.99, 90% interval 0.8 to 1.23.
Homologues: Orthologues: chimpanzee ZBTB14 (100% identical), macaque ZBTB14 (100% identical), dog ZBTB14 (99% identical), pig ZBTB14 (99% identical), rabbit ZBTB14 (99% identical), mouse Zbtb14 (99% identical), rat Zbtb14 (99% identical), guinea pig ZBTB14 (95% identical), tropical clawed frog zbtb14 (90% identical), zebrafish zbtb14 (75% identical), zebrafish zbtb38 (30% identical). Paralogues in human: BCL6 (23% identical), ZBTB21 (23% identical), ZBTB49 (22% identical), BCL6B (21% identical), ZBTB46 (20% identical), ZBTB33 (20% identical), ZBTB7B (18% identical), ZBTB25 (17% identical), ZBTB26 (17% identical), NACC2 (17% identical), GFI1 (17% identical), PRDM13 (17% identical), and 16 more.
Diseases named in the same sentence as ZBTB14 in open-access papers:
ZBTB14 is named in the same sentence as 13 diseases in open-access papers, as found by Europe PMC text mining. Sharing a sentence is not in itself a finding about the gene and the disease. The quoted sentences say what the papers report.
acute myeloid leukemia (1 paper, 2022). Acute myeloid leukemia (AML) is a group of neoplasms arising from precursor cells committed to the myeloid cell-line differentiation. "Recently, a missense mutation of ZBTB14 gene (ZBTB14S8F) was detected by whole-exome sequencing in a newly diagnosed acute myeloid leukemia (AML) patient." (PMID 36205309, 2022). "Moreover, a serine to phenylalanine mutation found in an acute myeloid leukemia (AML) patient could target ZBTB14 protein to autophagic degradation." (PMID 36205309, 2022).
medulloblastoma (1 paper, 2022). A malignant, invasive embryonal neoplasm arising from the cerebellum. "Future studies are needed to understand the role of ZBTB14 in medulloblastoma and its epigenetic regulation with target genes." (PMID 35008416, 2022).
cancer (7 papers, 2016 to 2026). A tumor composed of atypical neoplastic, often pleomorphic cells that invade other tissues. "In addition, it has been reported that Znf161 (another alias of Zbtb14) knockout mice had a defect in genomic instability, which was associated with higher cancer risk." (PMID 36205309, 2022). "This included genes like, PIK3R2, PIK3CA, BIRC2 and ZBTB14 with implications in cancer that were over-expressed with FC above ≥10 in OS-DW in comparison to OS-R; while, expression of WNT5A, PIK3CB, ACVR1, MAPK13 and GBX2 were significantly reduced." (PMID 31690262, 2019). "Intersecting the sets of pan-cancer compensated and toxic genes yields nine high-confidence ARGOS genes, six of which are also frequently amplified: RBM12, RBM14, SNRPA, ZBTB14, POU2F1, and CDKN1A." (PMID 39870664, 2025). "Based on this strategy, we did not consider some highly enriched TFs that did not display matching expression such as ZBTB14 in CpG-rich hyper-methylated DMRs in all cancers (except CHOL and THCA), confirming findings from a previous pan-cancer analysis." (PMID 35331302, 2022).
blood cancers (1 paper, 2025). "Highly analogous behaviour is exhibited by ZBTB family members BCL6 (aka ZBTB27) and the Drosophila Abrupt protein (probably ZBTB14) in blood cancers." (PMID 40460875, 2025).
ZBTB14 also shares sentences with these, for which no sentence is quoted: tumor (6 papers); breast carcinoma (4); colon adenocarcinoma (2); colorectal cancer (2); breast tumors (1); hepatocellular carcinoma (1); myopia (1); type 2 diabetes (1); vulvar cancer (1).